XPC (XPC complex subunit, DNA damage recognition and repair factor)
Diseases named in the same sentence as XPC in open-access papers (continued):
Sharing a sentence is not in itself a finding about the gene and the disease.
Hearing impairment (1 paper, 2023). A decreased magnitude of the sensory perception of sound. "Moreover, XPC c.2815AA genotype was associated with greater odds of severe hearing impairment, with a reported OR of 3.13 (p = 0.01) in the multivariate regression model." (PMID 36980643, 2023). "In associations of SNVs, it was observed that patients with GSTM1 null plus the XPC c.2815AA genotype had 8.19 greater odds of having moderate/severe hearing impairment (p = 0.02, PA = 99%)." (PMID 36980643, 2023).
Hodgkins lymphoma (1 paper, 2024). A heterogeneous group of malignant lymphoid neoplasms of B-cell origin characterized histologically by the presence of Hodgkin and Reed-Sternberg (HRS) cells in the vast majority of cases. "Despite this, the association between XRCC1 Arg/Gln and XPC Lys/Lys was found to decrease the risk of developing Hodgkin’s disease (OR = 2.14; 95% CI = 1.09−4.23)." (PMID 38541232, 2024).
Hyperglycemia (1 paper, 2021). An increased concentration of glucose in the blood. "The recognition that NER genes including XPC, XPA, XPD, CSA, CSB, and XPG possess HREs prompted us to interrogate whether hyperglycemia-induced destabilization of HIF-1α contributed to NER attenuation." (PMID 34426491, 2021).
lactic acidosis (1 paper, 2019). Metabolic acidosis characterized by the accumulation of lactate in the body. "For example, transduction of siRNA of XPC into human keratinocytes induces lactic acidosis which resulted in suppressed expression of mitochondrial OXPHOS subunits and upregulation of enzymes associated with glycolysis." (PMID 31551763, 2019).
metabolic syndrome (1 paper, 2021). A cluster of metabolic risk factors for CARDIOVASCULAR DISEASES and TYPE 2 DIABETES MELLITUS. "Furthermore, it will be of interesting to assess XPc therapeutic potential in G6PD-deficient patients as proposed for AG1 and its derivatives as well as in the predisposed metabolic syndrome patients." (PMID 34679753, 2021).
metastatic tumors (1 paper, 2011).
myeloproliferative neoplasm (1 paper, 2024). A clonal hematopoietic stem cell disorder, characterized by proliferation in the bone marrow of one or more of the myeloid (i.e., granulocytic, erythroid, megakaryocytic, and mast cell) lineages. "We also wanted to establish the association between the studied polymorphisms of the XPC, XPD, XPF, and XPG genes and the JAK2, CALR driver mutations and to identify possible predictors in the appearance of myeloproliferative neoplasms." (PMID 38541232, 2024). "We hypothesized that the XPC, XPD, XPF, and XPG gene polymorphisms influence the appearance of myeloproliferative neoplasms (MPNs)." (PMID 38541232, 2024).
oral cancer (1 paper, 2025). "A/C allele polymorphism in XPC is associated with smoking and may increase the risk of smoking-related oral cancer." (PMID 40157540, 2025).
ototoxicity (1 paper, 2017). damage to the ear, specifically the cochlea or auditory nerve as a result of some toxic stimulus, eg from a drug. "Patients with XPC c.2815AC or CC and XPD c.934GA or AA genotypes had 0.20 and 0.38 less chances of presenting moderate/severe ototoxicity and nausea, respectively." (PMID 26918827, 2017).
preeclampsia (1 paper, 2021). Preeclampsia is a hypertensive disorder of pregnancy that is characterized by new-onset hypertension with proteinuria presenting after 20 weeks of gestation, and depending on mild or severe forms may initially present with severe headache, visual disturbances, and hyperreflexia. "Xeroderma pigmentosum complementation group C (XPC) is a DNA damage recognition protein that plays an important role in nucleotide excision repair and can reduce oxidative stress, which may be involved in the development of preeclampsia (PE)." (PMID 34802422, 2021).
progeroid syndrome (1 paper, 2024). A group of rare genetic disorders which mimic physiological aging, making affected individuals appear to be older than they are. "Firstly, we tested our network exclusively containing progeroid syndromes by raising the threshold, which led to the syndromes GO, XPC, XPF and XPV to disconnect from the rest." (PMID 38345566, 2024).
Pruritus (1 paper, 2019). Pruritus is an itch or a sensation that makes a person want to scratch. "Symptoms of pruritus resulted associated at t1 with a 0.79-fold change of XPC and with a 1.01-fold change of ZMAT3; at t2 pruritus was associated with a 0.87-fold change of ATM, and a lower BCL2/BAX ratio (respectively, 0.76- vs. 1.15-fold change)." (PMID 31632918, 2019).
renal cell carcinoma (1 paper, 2026). "Furthermore, the combination of AT-II and AT-III with FDA-approved drugs enhanced sensitivity in XPC-KD-resistant renal cell carcinoma (RCC) cells, overcoming XPC deficiency-mediated resistance." (PMID 41599296, 2026).
severe combined immunodeficiency (1 paper, 2018). Severe combined immunodeficiency (SCID) comprises a group of rare monogenic primary immunodeficiency disorders characterized by a lack of functional peripheral T lymphocytes resulting in early-onset severe respiratory infections and failure to thrive. "Additionally, various companies managed to develop procedures to modify MN for use in genome editing to induce targeted recombination and correction of the RAG1 gene related to severe combined immunodeficiency (SCID) or XPC gene associated with xeroderma pigmentosum in skin cells." (PMID 29344676, 2018).
cancer (94 papers, 2005 to 2025). A tumor composed of atypical neoplastic, often pleomorphic cells that invade other tissues. "Rs2228001 has equally been suggested to possibly influence XPC's functionality and modulate the risk of various other cancers." (PMID 40833230, 2025). "XPC deficiency differentially impacts cancer and bronchial epithelial cell susceptibility to cell death through apoptosis during cigarette smoke exposure." (PMID 40060594, 2025). "Across cancers, we found that heterozygous loss events in XPC (2/5 tumor types), POLK (4/5), LIG4 (5/5), ATM (3/5), and TP53BP1 (3/5) were common in MYBL2 High tumors." (PMID 36358918, 2022). "Decreased XPC mRNA and protein expression has been described in a number of cancers, with gene polymorphisms, deletions, and transcriptional regulation all active areas of research in the regulation of XPC expression." (PMID 35530314, 2022). "High expression of miRNA-346, commonly elevated in NSCLC and other cancers, was associated with lower XPC mRNA and protein expression, indicating another potential mechanism for XPC downregulation in human cancers." (PMID 35530314, 2022). "Numerous cancers are associated with decreased XPC expression, but the mechanism by which this occurs is less clear." (PMID 35530314, 2022). "Studies showed that low expression or mutation of XPC positively is related to cancer occurrence and drug resistance during cancer treatment." (PMID 34803670, 2021). "There is a controversial conclusion regarding the genetic impacts of the XPC rs2228000 SNP in the risk of clinical cancer diseases in different publications." (PMID 31710080, 2019). "Overall, evidence strongly suggests that XPC rs2228001 genotype is associated with altered DNA repair capacity, establishing ground for a putative role of this SNP in cancer susceptibility." (PMID 31374908, 2019). "The present study investigated the potential genetic role of nonsynonymous XPC rs2228000 in the risk of different clinical types of cancer by pooling published studies with inconclusive conclusions." (PMID 31710080, 2019). "The abnormal expression of the XPC protein was also reportedly linked to the progression of the cancer." (PMID 31710080, 2019). "Only three prior meta-analyses with fewer than 15 studies in 2008 and one meta-analysis with 33 articles in 2013 were reported to detect the genetic association between XPC rs2228000 and overall cancer risk." (PMID 31710080, 2019). "After retrieving these studies, only three previous meta-analyses with no more than 15 studies in 2008 and one meta-analysis with 33 studies in 2013 were performed to assess the genetic association of XPC rs2228000 and the risk of overall cancer." (PMID 31710080, 2019). "XPC-deficient transgenic mice are highly predisposed to several types of cancer and XPC/GADD45a knockout in mice leads to development of lung tumors." (PMID 28746345, 2017). "Reduced expression of XPC has been associated with reduced repair of UV-induced photoproducts and increased cancer incidence." (PMID 27391141, 2016). "Two common nonsynonymous polymorphisms in the XPC gene, Lys939Gln (rs2228001 A > C) and Ala499Val (rs2228000 C > T), have been investigated in various types of cancer." (PMID 27669310, 2016). "Previous studies have identified that XPC gene polymorphisms were associated with various types of cancer." (PMID 27847809, 2016). "Meta-analyses till date have analyzed XPC polymorphisms for correlation with overall cancer risk and the risk of specific cancers." (PMID 27246180, 2016). "There is now sufficient evidence to conclude that XPC polymorphisms increase the risk of cancer, particularly UBC." (PMID 27246180, 2016). "A meta-analysis focused on the role of XPC in carcinogenesis, which revealed two SNPs in XPC (rs2228001 and rs2228000) that were significantly associated with overall cancer risk." (PMID 25391773, 2015).
cancer (continued). "Our data indicates that the deficiency of XPC promotes the expression of Snail, which further represses the expression of E-Cadherin to rescue cancer cells from E-Cadherin-mediated proliferation inhibition." (PMID 25871391, 2015). "Certain NER pathway polymorphisms, such as Ala499Val and Lys939Gln in the XPC gene, have been shown to associate with overall cancer risk." (PMID 25962431, 2015). "We also found two recent meta-analyses focused on the overall cancer risk and XPC gene polymorphisms." (PMID 24643114, 2014). "For example, the Lys939Gln and Ala499Val as well as the ploy (AT) deletion/insertion polymorphisms of the XPC gene were significantly associated with an increased overall cancer risk." (PMID 24643114, 2014). "Recently, He J and colleagues performed a comprehensive meta-analysis about XPC Lys939Gln and Ala499Val polymorphisms and cancer susceptibility." (PMID 24736739, 2014). "XPC knock-out transgenic mice studies reveal the high incidence of a predisposition to many types of cancer." (PMID 25535740, 2014). "Deficiency or attenuation of the XPC protein has been strongly associated with high incidence of cancer." (PMID 21507255, 2011). "Nevertheless, PAT polymorphism in the XPC gene has been associated with an increased risk of developing different types of cancer, including smoking-related cancers or melanoma." (PMID 17705814, 2007). "This may also inform carcinogenesis mechanisms across other cancer types, as an increased prevalence of XPC deletions or polymorphisms has been described in lung, prostate, bladder, hematologic, and other cancers." (PMID 40060594, 2025). "There have been many studies suggesting that XPA and XPC polymorphisms had a significant effect on the risk of cancer and disease, and they could be a biomarker." (PMID 37510255, 2023). "Polymorphisms in the ERCC1 and XPC genes may influence the genomic stability then modify the disease risk, especially cancers." (PMID 35693108, 2022). "Two nonsynonymous single nucleotide polymorphisms (SNPs), c.2815G > T (p.Q939E, rs2228001) in exon 16 and c.1496C > T (p.A499V, rs2228000) in exon 9 of XPC may alter the capacity of XPC and modulate risk of various cancers." (PMID 34802422, 2021). "Moreover, XP patients with defective XPC or XPE genes have >1000 times higher incidence of cancer (10-fold the risk for visceral cancers)." (PMID 33019598, 2020). "The identification of genes and the pathways regulated by XPC will give a more global view of the role of XPC as a Pol II cofactor and will help to identify relevant markers for an early and specific diagnosis, and to anticipate/predict the cancer risk among the different symptoms." (PMID 29973595, 2018). "For XPC, a meta-analysis for Lys939Gln (rs2228001) of 62 studies including 25708 cases and 30432 controls confirmed an increased cancer risk associated with this polymorphism in the homozygous genetic model for Asian populations, but not for other ethnic groups." (PMID 27974699, 2017). "XPC gene polymorphisms are involved in the different types of cancer." (PMID 27847809, 2016). "In addition to its role in carcinogenesis, XPC deficiency is also associated with a poor prognosis of various cancer patients." (PMID 25871391, 2015). "A previous study has shown that overexpression of two NER genes, ERCC1 and XPC, is associated with liver fibrogenesis and cancer and could be related to the well-recognized resistance of HCC to chemotherapeutics." (PMID 24877058, 2014). "XPC polymorphisms and cancer risk has been investigated by several meta-analyses." (PMID 24736739, 2014). "Overexpression of two key genes involved in the early steps of the NER process, ERCC1 and XPC, is associated with liver fibrogenesis and cancer and could be related to the well-recognized resistance of HCC to chemotherapeutics." (PMID 24877058, 2014).
cancer (continued). "Polymorphisms in the XPC gene may influence the function of the protein and an individual’s DNA repair capacity, and thereby affect genetic instability and modify individual predisposition to cancer." (PMID 27669310, 2016). "Therefore, XPC polymorphisms appear to significantly increase cancer risk." (PMID 27246180, 2016). "Because mutations in XPC cause a high risk of cancer in XP patients, we hypothesized that inherited sequence variations in XPC may alter DNA repair and thus susceptibility to cancer." (PMID 17498315, 2007). "XPC is increasingly recognized as an important player in solid organ cancer development and response to cancer therapeutics, both through its canonical role in GG-NER and through other repair pathways." (PMID 35530314, 2022). "It is important to note the mounting evidence highlighting an important link between the role of XPC in DNA repair, DNA damage response and transcriptional regulation and cancer development." (PMID 35530314, 2022). "These modifications, which regulate XPC function in GG-NER repair and the downstream DNA damage response, are likely to impact cancer risk and response to therapy, although this specific link requires more study." (PMID 35530314, 2022). "Pathogenic variants in five “other” cancer predisposition genes (ALK, BUB1B, FANCG, RB1 and XPC) exclusively investigated for truncating variants, were identified in seven patients." (PMID 35039564, 2022). "As the local tumor immune response is increasingly recognized as critical to solid organ cancer development, the role of XPC in local tumor microenvironment, including immune escape, warrants further investigation." (PMID 35530314, 2022). "XPC-mutated cells are, therefore, photosensitive and accumulate UVB-induced pyrimidine dimers leading to increased cancer incidence." (PMID 34360928, 2021). "To further determine the protein expression level of XPC in cancer tissue and paracancerous tissue, we collected fresh lung adenocarcinoma cancer tissue and paracancerous tissue for Western blot analysis." (PMID 34803670, 2021). "Both oroxylin A treatment and XPC knockdown augment anti-cancer efficacy of cisplatin in vitro, indicating that oroxylin A alleviates hypoxia-induced cisplatin resistance at least partly through downregulating XPC." (PMID 34575983, 2021). "It was reported that SNV in the XPC gene are potential markers of treatment response to oxaliplatin-based therapy in cancer patients." (PMID 35056973, 2021). "Overexpression of XPC in several types of cancer cells (e.g., lung, colorectal, and gastric cancers) leads to elevated cisplatin resistance." (PMID 33291532, 2020). "Consistent with this notion, studies performed in cancer cell lines have shown a correlation between XPC protein levels and cisplatin resistance." (PMID 33291532, 2020). "Considering the limitations of our study, we need to analyze more publications to verify the genetic impact of XPC rs2228000 in other types of cancer." (PMID 31710080, 2019). "It would be valuable to carry out an integrated analysis to evaluate the combined role of more XPC polymorphic loci (e.g., rs2228001, PAT−/+) in susceptibility to different types of cancer based on the available evidence." (PMID 31710080, 2019). "Although several meta-analyses of XPC rs2228000 and certain specific cancer types exist, differences in study enrolment, data extraction, analysis strategy, and result descriptions were observed." (PMID 31710080, 2019).